SIRT1 (sirtuin 1)
Diseases named in the same sentence as SIRT1 in open-access papers (continued):
Sharing a sentence is not in itself a finding about the gene and the disease.
peripheral nerve injury (4 papers, 2022 to 2025). Injury to a peripheral nerve. "SIRT1 plays a key role in neuropathic pain caused by peripheral nerve injury by reducing oxidative stress and inflammation." (PMID 41517346, 2025). "In this review, we summarize recent progress in understanding the roles and mechanisms of SIRT1 in mediating chronic pain associated with peripheral nerve injury, chemotherapy‐induced peripheral neuropathy, spinal cord injury, bone cancer, and complete Freund's adjuvant injection." (PMID 35396903, 2022). "SIRT1 is known to play a critical role in peripheral nerve injuries, primarily through its ability to reduce oxidative stress and inflammation." (PMID 41517346, 2025). "The promotion of endogenous H2S production via S-propargyl-cysteine leads to SIRT1 upregulation and microvascular reconstruction following peripheral nerve injury." (PMID 39598406, 2024). "Most studies have used animal models of peripheral nerve injury to explore the relationship between SIRT1 expression and neuropathic pain." (PMID 35396903, 2022). "SIRT1 activation by H2S-induced NAD+ elevation led to interaction with NICD under hypoxic conditions, negatively regulating Notch signaling in micro-endothelial cells to promote sprouting and ameliorate peripheral nerve injury." (PMID 39598406, 2024). "Considering the important role of SIRT1 in angiogenesis and the regulatory effect of H2S on SIRT1, we attempted to use the endogenous H2S donor SPRC as a regulator of SIRT1 to promote microvascular reconstruction under hypoxic condition after peripheral nerve injury." (PMID 36829853, 2023).
pituitary adenoma (4 papers, 2019 to 2025). "It was demonstrated that the SIRT1 rs7895833 G/G genotype was associated with an approximately 13-fold increased risk of developing active pituitary adenoma compared to carriers of the A allele (A/A or A/G genotypes)." (PMID 40507674, 2025). "The aim of the study was to find the association between SIRT1 concentration, SIRT1 rs3758391, rs3818292, rs7895833 polymorphisms and clinical manifestations of pituitary adenoma (PA)." (PMID 34942940, 2021). "In our study, we decided to evaluate the association between SIRT1 concentration, SIRT1 rs3758391, rs3818292, rs7895833 polymorphisms, and clinical manifestations of pituitary adenoma." (PMID 34942940, 2021). "That is why we aimed to investigate whether there was an association between pituitary adenoma and two other polymorphisms (rs4746720, rs3740051) of the SIRT1 gene." (PMID 31747893, 2019). "Our purpose was to determine if SIRT1 (rs4746720, rs3740051) genotypes have an influence on the development of pituitary adenoma (PA)." (PMID 31747893, 2019). "Therefore, we decided to investigate SIRT1 levels in patients with pituitary adenoma to know whether SIRT1 regulates metabolism in the brain and pituitary gland." (PMID 34942940, 2021).
premature ovarian failure (4 papers, 2023 to 2026). "A study has found that after FOXL2 mutation in mice, the promotion of SIRT1 is lost, accelerating follicular development and activating a large number of primordial follicles, leading to premature ovarian failure." (PMID 41007402, 2025). "In recent years, there have been increasing studies on the role of SIRT1 in anti-oxidative stress, but few studies have investigated its antioxidant effect in premature ovarian failure (POF)." (PMID 38228655, 2024).
retinal diseases (4 papers, 2014 to 2025). "Sirt1 plays an important role in various retinal diseases, including anti-oxidant and anti-apoptotic effects in mice." (PMID 30564112, 2018). "In contrast to limited in vivo studies of Sirt1 mutant mice in retinal diseases, small molecule Sirt1 activators have been evaluated in the eye in several studies." (PMID 24416337, 2014).
Rett syndrome (4 papers, 2013 to 2023). A severe neurodevelopmental disorder affecting the central nervous system. "In this way, a recent article described that the SIRT1-activator resveratrol increases KCC2 levels in human Rett syndrome neurons, which fits with our results." (PMID 32230770, 2020).
tendinopathy (4 papers, 2022 to 2025). "Both in rat cultured tenocytes and in Achilles’ tendons with collagenase-induced tendinopathy levels of IL6, ROS and NOX1 and NOX4 were increased while SIRT1 and SIRT6 were decreased together with SOD activity." (PMID 40023978, 2025). "In Achilles tendons with collagenase-induced tendinopathy, NMN increased the mRNA expression of SIRT1 and SIRT6, as well as SOD activity; while suppressing protein expression of NOX1 and NOX4, and mRNA expression of IL6." (PMID 35287653, 2022).
thoracic aortic aneurysm (4 papers, 2013 to 2024). An aneurysm formed in the wall of the proximal portion of the descending aorta proceeding from the arch of the aorta. "Recently, it has been observed that the GS-ylation of sirtuin-1 (SirT1) is involved in the pathogenesis of thoracic aortic aneurysms associated with Marfan syndrome." (PMID 39203889, 2024). "It has also been observed that the GS-ylation of SirT1 inhibits its activity contributing to the onset of thoracic aortic aneurysm in Marfan syndrome." (PMID 39203889, 2024). "The authors noted that melatonin administration prevented thoracic aortic aneurysm formation via acting on SIRT1 in a melatonin-receptor-dependent manner." (PMID 35991314, 2022). "Interestingly, a recent study highlighted the SIRT1-melatonin axis in a murine thoracic aortic aneurysm model." (PMID 35991314, 2022). "In the presence of bicuspid aortic valve, the demonstration of genetic alterations at the level of NOTCH-1 and SIRT-1 could suggest a strict monitoring of patients due to the higher likelihood to develop thoracic aortic aneurysm." (PMID 24453931, 2013). "Studies have shown that SIRT1 and SIRT6 reduces abdominal or thoracic aortic aneurysms by reducing the senescence and inflammation in VSMCs." (PMID 38673941, 2024).
tuberculosis (4 papers, 2022 to 2024). A chronic, recurrent infection caused by the bacterium Mycobacterium tuberculosis. "Furthermore, lower SIRT1 expression is connected with M. bovis infection as well as the pathogenesis of tuberculosis, indicating SIRT1 activators as a potential and effective host-directed therapeutic approach against tuberculosis." (PMID 36859519, 2023). "In addition, another assay not only confirmed the importance of sirtuin 1 in this model, but also showed that this molecule is reduced in human cases of active tuberculosis compared to healthy people, making Sirtuin 1 an interesting possible new biomarker of tuberculosis in humans." (PMID 36678397, 2022). "Therefore, the hypermethylation of Sirt1 in case group may participate in the process of active TB development by inhibiting the expression of Sirt1 mRNA and interfering the M. tuberculosis apoptosis." (PMID 35446152, 2022).
adenovirus infection (3 papers, 2015 to 2026). "Our findings not only highlight Dihydro-R as a promising therapeutic candidate for adenovirus infections but also provide insights into SIRT1-targeted antiviral strategies." (PMID 41399758, 2026). "Our study indicated that cardiac overexpression of SIRT1 by adenovirus infection did not have significant influence on blood glucose and serum TC and TG." (PMID 26489513, 2015).
adult T-cell leukemia/lymphoma (3 papers, 2015 to 2021). A peripheral (mature) T-cell neoplasm linked to the human T-cell leukemia virus type 1 (HTLV-1), adult T-cell leukemia/lymphoma is endemic in several regions of the world, in particular Japan, the Caribbean, and parts of Central Africa. "Phosphorylation of SIRT-1 by Cyclin/Cdk1 causes SIRT-1 overexpression in the cell cycle and increases the proliferation of malignant cells in adult T-cell leukemia-lymphoma (ATL), playing a critical role in pathogenesis of this disease.." (PMID 26865932, 2015).
Airway obstruction (3 papers, 2018 to 2024). Obstruction of conducting airways of the lung. "The positive correlation existing between SIRT1 activity in PBMCs and parameters of airway obstruction and its severity (measured by FEV1/FVC and FEV1, resp)." (PMID 29861836, 2018). "It is also known that the protein levels of SIRT1 were associated with the severity of the airways obstruction and have a strong negative correlation with the amount of cigarette consumption, suggesting that oxidative stress may lead to a decrease in SIRT1 levels (Kwon and Ott, 2008 ▶)." (PMID 32523885, 2020).
ankylosing spondylitis (3 papers, 2018 to 2024). An autoimmune chronic inflammatory disorder characterized by inflammation in the vertebral joints of the spine and sacroiliac joints.
Anorexia (3 papers, 2018 to 2024). Lack of desire to eat (loss of appetite). "In this study, we demonstrate that the brain-specific KO of SIRT1 in mice is protective against the AN phenotypes when subjected to the activity-based anorexia (ABA) model." (PMID 32499508, 2020). "Here the authors show that inhibition of SIRT1 is protective against the onset and progression of anorectic behavior in an activity-based anorexia model, suggesting SIRT1 could be a potential therapeutic target." (PMID 32499508, 2020). "Herein, we demonstrate that SIRT1 inhibition, both genetically and pharmacologically, delays the onset and progression of AN behaviors in activity-based anorexia (ABA) models, while SIRT1 activation accelerates ABA phenotypes." (PMID 32499508, 2020).
anxiety disorder (3 papers, 2015 to 2024). A category of psychiatric disorders which are characterized by anxious feelings or fear often accompanied by physical symptoms associated with anxiety. "Polymorphisms in the SIRT1 gene, such as SNPs (rs10997870, rs12778366), are associated with anxiety disorders, panic disorder, and social phobia." (PMID 39275174, 2024). "In an elegant study, both common and rare variations in SIRT1 in humans were found to associate with the increased odds for anxiety disorders at large." (PMID 26509718, 2015). "One aim of our current study was to confirm, as far as SIRT1 is concerned, the earlier findings that have demonstrated associations of sirtuins with depressive and anxiety disorders." (PMID 26509718, 2015). "SIRT1 polymorphisms have previously been associated with depressive and anxiety disorders." (PMID 26509718, 2015). "This is particularly relevant considering that SIRT1, the main target of RES, is implicated in stress–anxiety disorders." (PMID 39275174, 2024).
autoimmune hepatitis (3 papers, 2017 to 2022). Hepatitis caused by autoantibodies. "Additionally, we sought to determine the roles of SIRT1 and p66shc involved in Con A-induced autoimmune hepatitis in aged mice." (PMID 28578410, 2017). "However, it is still unknown whether SIRT1 and p66shc are involved in the immune dysregulation and dysfunction of liver regeneration in elderly humans with autoimmune hepatitis." (PMID 28578410, 2017). "Additionally, SIRT1 may have beneficial effects on autoimmune hepatitis." (PMID 36581622, 2022).
autoimmune thyroid disease (3 papers, 2020 to 2023). Inflammatory disease of the thyroid gland due to autoimmune responses leading to lymphocytic infiltration of the gland. "In line with this assumption, studies of single nucleotide polymorphisms have confirmed an association between IL-27 and the SIRT1 gene with autoimmune thyroid diseases." (PMID 34439776, 2021). "Moreover, the sirtuin 1 was positively correlated with IL-27 levels in women with T1DM and HD, which suggests an association with thyroid autoimmunity." (PMID 34439776, 2021).
bronchopulmonary dysplasia (3 papers, 2016 to 2025). Bronchopulmonary dysplasia is a chronic respiratory disease that results from complications related to lung injury during the treatment of infant acute respiratory distress syndrome in low-birth-weight premature infants or from abnormal lung development in older infants.
cervical (3 papers, 2009 to 2025). "Together, these data support our previous studies demonstrating that SIRT1 modulates WRN expression in a posttranslational manner (i.e., by deacetylation) and suggest that the SIRT1-WRN axis may contribute to cervical disease progression." (PMID 32938703, 2020). "To investigate this, we utilized cervical liquid-based cytology samples from a cohort of HPV16+ patients representing the progression of cervical disease (CIN1 to CIN3) and compared this to HPV- normal cervical tissue for SIRT1/WRN protein and mRNA expression." (PMID 32938703, 2020). "Wenow present evidence that SIRT1, an aging-related NAD-dependentdeacetylase, mediates HPV E7 survival function in SiHa cervical cancercells." (PMID 20157519, 2009). "Furthermore, the role of SIRT1 is particularly important in the context of HPV infection, with recent studies showing that SIRT1 interacts with HPV oncogenes and contributes to cervical tumorigenesis." (PMID 41300302, 2025). "SIRT1 expression increases progressively from normal cervical epithelium to low-grade and high-grade cervical intraepithelial neoplasia (CIN) and invasive squamous cell carcinoma (SCC), suggesting its involvement in cervical carcinogenesis." (PMID 41300302, 2025).
Cholestatic liver disease (3 papers, 2019 to 2022). "In this study, we demonstrate that SIRT1 regulates liver inflammation by controlling the activation of macrophages in response to endotoxin and during cholestatic liver disease." (PMID 34952202, 2022). "Finally, PEPC-Boy mice were used for adoptive transfer experiments to elucidate the impact of SIRT1-overexpressing macrophages in contributing to cholestatic liver disease." (PMID 34952202, 2022). "Overall, our results provide novel mechanistic insights into the role of SIRT1 in regulating liver inflammation and warrant future research to define the potential of metabolic regulation of macrophages, via modulating SIRT1, as a therapeutic approach to treat cholestatic liver disease." (PMID 34952202, 2022). "Here, we define the role of sirtuin 1 (SIRT1), a main metabolic regulator, in controlling the activation of macrophages during cholestatic liver disease and in response to endotoxin." (PMID 34952202, 2022). "Sirtuin 1 (SIRT1) regulates liver regeneration and bile acid metabolism by modulating farnesoid X receptor (FXR); we here investigate its role in cholestatic liver disease." (PMID 30229970, 2019).
clear cell carcinoma (3 papers, 2019 to 2023). "This study aimed to determine the expression of SIRT1 in endometrioid and clear-cell carcinomas of the uterus and to analyze potential correlations to clinical pathological characteristics including survival." (PMID 32388637, 2020). "The expression of SIRT1 in uterine and ovarian endometrioid and clear-cell carcinomas correlated significantly with a high expression of β-Catenin in the membrane (p = 0.028; ρ = 0.333, p = 0.011)." (PMID 32388637, 2020). "The expression of SIRT1 was significantly higher in endometrioid carcinoma (median: 4; SD ± 2.66) compared to clear cell carcinoma (median: 0; SD ± 2.01; p = 0.007)." (PMID 32388637, 2020). "Until now, there are only few studies focusing on SIRT1 as prognostic factor in endometrial and clear cell carcinomas of the uterus." (PMID 32388637, 2020). "In Hendrix’s dataset, SIRT1, SIRT3, and SIRT4 expression levels were significantly lower in serous, endometrioid, mucinous, and clear cell adenocarcinoma than they were in normal ovarian tissues." (PMID 31572453, 2019).
congenital heart disease (3 papers, 2016 to 2023). A heart disease that is present at birth. "Growing experimental evidence supports a role of Sirt1 in the development of congenital heart diseases." (PMID 29497772, 2018). "Furthermore, reduction of the activity and/or expression of Sirt1 and Sirt3 in different fetal tissues has been described in maternal conditions favoring occurrence of congenital heart diseases, such as gestational diabetes and obesity." (PMID 29497772, 2018). "Therefore, the Nkx2.5/SIRT1 negative feedback regulatory loop may potentially be involved in cardiomyocyte survival during cardiogenesis and congenital heart diseases." (PMID 27819261, 2016).
coronary atherosclerosis (3 papers, 2013 to 2024). Atherosclerosis of the coronary vasculature. "It was found that activation of SIRT1 can inhibit autophagy-dependent ferroptosis, and alleviate coronary atherosclerosis in mice." (PMID 36188570, 2022). "In the present study, we report that monocyte Sirt1 gene expression is decreased in patients suffering from coronary atherosclerosis; in line with this, expression of Sirt1-negatively regulated downstream target interleukin-6 (IL-6) was increased in the same patient groups." (PMID 23382833, 2013). "However, whether the impaired Sirt1 levels in patients suffering from coronary atherosclerosis are a result of the atherosclerotic process itself or vice versa, cannot be answered by this study." (PMID 23382833, 2013).
ductal adenocarcinoma (3 papers, 2015 to 2022). "It was further demonstrated that pharmacologic inhibition of SIRT1/2 caused a marked reduction in aromatase protein levels and SIRT1 immunohistochemistry showed a significant up-regulation in invasive ductal carcinoma relative to normal tissue adjacent to tumor." (PMID 25569080, 2015).
encephalitis (3 papers, 2015 to 2025). An acute inflammatory process affecting the brain parenchyma. "In the context of HIV, SIRT1 expression is decreased in the gut of SIV-infected rhesus macaques and in macrophages/microglia of NHPs with SIV-encephalitis." (PMID 39149452, 2024). "Post-SIV infection, a significant upregulation of miR-142 was noted that leads to down-regulation of SIRT1, potentially contributing to SIV replication and SIV-induced encephalitis." (PMID 26483757, 2015).
endometritis (3 papers, 2024). An acute or chronic, usually bacterial infectious process affecting the endometrium. "Of these, 48 (78.7%) consented for endometrial biopsy to rule out endometritis and test for BCL6 and/or SIRT1." (PMID 38999962, 2024).